CTLA4 (cytotoxic T-lymphocyte associated protein 4)
Diseases named in the same sentence as CTLA4 in open-access papers (continued):
Sharing a sentence is not in itself a finding about the gene and the disease.
tumor (continued). "Each CD44+ cell-type functions immunosuppression through different ways: CD44+ tumor cells express CD276, IL13, VEGFA, and IDO1; CD44+ TAMs express IL10, TGFB1, VEGFA, and HAVCR2; CD44+ T cells express CD274, TGFB1, CTLA4, LAG3, and PDCD1." (PMID 35187044, 2021). "Adding the immune checkpoint inhibitor-anti CTLA-4 antibody to the TIL culture allows one to overcome such anergy by promoting the outgrowth of TILs and enhancing their anti-tumor reactivity." (PMID 34885169, 2021). "For instance, tumour cells can create an immunosuppressive tumour microenvironment (TME) via the recruitment of immune-suppressive cells, like CTLA-4 expressing T-regulatory cells (Tregs) or Myeloid-derived Suppressor Cells (MDSC)." (PMID 35052732, 2021). "For example, activation of IFN-I signaling was shown to be correlated with abscopal effects of the combination therapy of anti-CTLA-4 and RT, which were abrogated when IFNAR1 was knocked down in tumor cells." (PMID 34830176, 2021). "Among the various approaches, immune-checkpoint inhibitors that target CTLA-4 as well as the PD1–PDL1 interaction, enabling an enhanced T cell-dependent anti-tumor response, have revolutionized the treatment of advanced melanoma and other cancers." (PMID 32850393, 2020). "In another study, it was reported that elevated expression of CTLA-4 and TIGIT genes in human CRC tumor tissues is driven by DNA hypomethylation." (PMID 32760400, 2020). "The three proteins, CTLA4, REG4, and ABCC12, which were regulated by both CAP and H2O2 have been known to be involved in tumor cell growth or drug resistance." (PMID 32947888, 2020). "Immuno‐antibodies that target immune check point such as CTLA‐4, PD1 and PD‐L1 have significantly improved survival in several tumours." (PMID 32227579, 2020). "No significant improvements were seen in the group treated with a CTLA-4 antibody and INT230-6 (22% CR) (2/9) compared to INT230-6 monotherapy in this single tumor model." (PMID 32599852, 2020). "Other negative regulators, as already discussed, are the immune checkpoints expressed by tumor cells and myeloid-derived cells, such as PD-L1 and CD80/CD86, respectively, which interact with PD-1 and CTLA-4 expressed on the T cell surface." (PMID 35582441, 2020). "Cytotoxic T lymphocyte antigen 4 (CTLA-4, also known as CD152) can affect the activation of T cells and inhibit the anti-tumor response." (PMID 33327297, 2020). "To address checkpoints, we administered IL-15 in combination with antibodies to PD-L1 and cytotoxic lymphocyte antigen-4 (CTLA-4) in the CT26 and MC38 colon carcinoma and TRAMP-C2 prostatic cancer syngeneic tumor models." (PMID 32508818, 2020). "Starting 7 days after tumor implant, EC2629 (0.1 μmol/kg, BIW for 3 weeks) was administered intravenously alone and in combination with anti-CTLA-4 antibody (250 μg, BIW for 2.5 weeks)." (PMID 32728172, 2020). "In light of unprecedented efficacy observed in multiple, historically difficult to treat tumor types using PD-1, PDL-1 and CTLA-4, inhibitors (CPIs), we now benefit from seven U.S. FDA approved drugs across sixteen indications between years 2011 and 2019." (PMID 32258034, 2020). "Finally, we described immune parameters in mice and patients associated with high systemic levels of butyrate but we did not identified a specific pathway affected by butyrate that could be blocked in order to restore anti-tumor activity of anti-CTLA-4 blockade in hosts with high systemic butyrate." (PMID 32358520, 2020). "In Lewis Lung Carcinoma tumours pemetrexed and sildenafil interacted to further supress tumor growth, which was then enhanced by administration of either anti-PD1 or anti-CTLA4 checkpoint inhibitory antibodies." (PMID 31885880, 2020). "In agreement with previous reports, we observed differential CTLA4 expression by Tregs in spleen and tumors of CT26 tumor bearing mice, while Tregs from the colon lamina propria express an intermediate level of CTLA4." (PMID 33127658, 2020).
tumor (continued). "It proved that adoptive transfer tumor-infiltrating lymphocytes (TIL) that had been pretreated in vitro with anti-PD-1 and anti-CTLA-4 antibodies eliminated tumors in vivo." (PMID 33585182, 2020). "In HCC, we observed increased expression of several more activation- (IFNG, CD38, IL2RA, TNFRSF9) and exhaustion-related (TIGIT, CTLA4, PDCD1, ENTPD1) genes in tumor MAIT cells." (PMID 32849590, 2020). "We found several signs of immune suppression in tumours compared to adjacent non-malignant tissues, including T cells more often expressing the immune checkpoint molecules programmed cell death protein (PD-1) and cytotoxic T lymphocyte-associated protein 4 (CTLA-4)." (PMID 33228141, 2020). "Together, these data suggest that TOX, and potentially TIM-3, CTLA-4, VISTA, TIGIT, KLRG1, TOX2, SIRT1, Ki-67, and Helios mRNA levels in CRC tumor tissues increase in advanced disease stages, suggesting their possible roles in CRC progression." (PMID 32393998, 2020). "Combined treatment with the FATP2 inhibitor lipofermata and checkpoint inhibitors anti-CTLA-4 or anti-CSF-1R inhibitors abolished the inhibitory activity of PMN-MDSCs and blocked tumor progression in mice." (PMID 32942545, 2020). "The distinct expression of PD1 and CTLA4 in immune cells and PDL1 in tumor cells, respectively, would explain these apparent contradictory findings." (PMID 32719800, 2020). "It has been reported that PD-1, CTLA-4, TIM-3 and TIGIT were hypomethylated in tumour tissues, compared to the normal tissues, and they also exhibited reduced H3K9me3 and H3K27me3 at their promoters." (PMID 32340605, 2020). "These humanized monoclonal antibodies target inhibitory receptors (e.g. CTLA-4, PD-1, LAG-3, TIM-3) and ligands (PD-L1) expressed on T lymphocytes, antigen presenting cells and tumor cells and elicit an anti-tumor response by stimulating immune system." (PMID 33162990, 2020). "Among the tumor-infiltrating CD4 T cells, essentially all of the Foxp3+ population expressed high levels of cell surface CTLA-4." (PMID 31991588, 2020). "It has been found that in tumor cells, immune checkpoints can lead to NK cell dysfunction, blocking these immune checkpoints (e.g. TIM-3, NKG2A, CTLA-4, PD-1, KIR2DL-1/2/3, CD96, TIGIT) can restore the function of NK cells." (PMID 33614486, 2020). "Treatment with immune blockade of CTLA4 and PD1 cell surface proteins on lymphocytes and tumor cells results in remarkable anti-tumor activity but can be accompanied by severe irAE." (PMID 32290812, 2020). "PD-1, TIM-3, CTLA-4, LAG-3, and CD244 mRNA levels were relatively similar amongst the different grades of tumor budding." (PMID 32393998, 2020). "Moreover, the expression of immune checkpoint proteins (PD-1, Tim-3, CTLA-4) by tumor-infiltrating lymphocytes known to be involved in the inhibition of T lymphocyte activation/proliferation could also be a factor in causing peripheral lymphopenia in cancer patients." (PMID 33207589, 2020). "Combination of CTLA-4 mAbs and IL36 expression produced much greater antitumor efficacy with reduced tumor growth rates and much prolonged survival." (PMID 32351508, 2020). "ICIs counteract the mechanisms used by tumor cells to suppress the immune system targeting PD1, PDL1, and CTLA-4." (PMID 32542150, 2020). "To date, impressive progress has been made in a variety of tumor treatments; PD1/PDL1 and CTLA4 inhibitors have been approved for clinical use in some tumors." (PMID 32944390, 2020). "Based of tumor-specific Treg depletion in CTLA-4 targeting therapy, the new generation of anti-CTLA-4 therapies should be more effective against tumors with the potential for significant Treg depletion." (PMID 31991588, 2020). "CTLA-4 is expressed on activated T cells, whereas CD80/86 is expressed on APCs, including tumor cells." (PMID 33102516, 2020). "The best characterized pathways are the interactions between CTLA-4 and CD80/86, and the binding of PD-1 to PD-L1 to tumor cells." (PMID 32602545, 2020).
tumor (continued). "We found that mRNA levels of PD-1, TIM-3, CTLA-4, TIGIT, CD160, CD244, and KLRG1 were elevated in CRC tumor tissue, implicating their potential contribution to CRC development and/or progression." (PMID 32393998, 2020). "However, checkpoint inhibitors currently used to target CD8+ T cells (e.g., anti-CTLA-4 and/or anti-PD-1 mAbs) have not been shown to be efficient for all tumor types and may cause a partial remission in the majority of tumors." (PMID 32099064, 2020). "Triple ICB resulted in a decreased tumor growth and enhanced response (11/13 vs. 6/13) to ICB therapy when compared with ICB targeting PD-1 and CTLA-4 only." (PMID 32071302, 2020). "To verify that FABP5highCD8+ T cells are exhausted, we tested the expression of additional exhaustion markers (TIM3, CTLA4, and LAG3) in cells from tumor sample by flow cytometry." (PMID 32611686, 2020). "In another study it was shown that CTLA-4 blockade leads to the enhanced proportion of IFN-γ producing CD4+ ICOShi effector T cells to Tregs in peripheral blood and tumor tissues of patients with bladder cancer." (PMID 33519807, 2020). "Because of reduced signaling of these regulators, tumor-residing CD8+ T-cells upregulate checkpoint molecules, such as PD-1, CTLA-4, LAG-3, and TIM-3, reflecting the exhausted state of these cells." (PMID 33072086, 2020). "In some tumor cells, an increase in IFN‐γ has been demonstrated to induce an increase in IDO production, further promotes resistance to monoclonal antibody CTLA‐4 or PD‐1 treatment, leading to immune escape, which can be overcome by IDO inhibitors." (PMID 32875727, 2020). "Lastly, we found a correlation between the hydra-identified tumor microenvironment subtype and CD274 and CTLA4 expression." (PMID 32275708, 2020). "Mouse studies show that blockade of the CTLA-4 and PD-1 receptors synergistically induce CD4 and CD8 T cell numbers in the tumor microenvironment (TME)." (PMID 32547707, 2020). "DCs cocultured with CTLA-4+ breast cancer cells expressed lower amounts of HLA-DR and costimulatory molecules, inhibited CD4+ and CD8+ T cell differentiation, and facilitated tumor growth." (PMID 35310881, 2020). "We then determine the effectiveness of this gene therapy strategy for delivery of IL36 expression plasmids to tumor and synergy between the IL36 gene therapy and CTLA-4 mAbs." (PMID 32351508, 2020). "Thus, anti-CTLA-4 treatments may restore immune responses to attack tumor cells." (PMID 32847045, 2020). "The mouse tumor cell line expressed little CTLA-4, but when growth was induced, these tumors showed high tracer uptake on the 64Cu-DOTA-anti-CTLA-4 PET scan, which correlated with higher influx of tumor infiltrating lymphocytes." (PMID 32042331, 2020). "Immune checkpoint receptors, including PD-1 and CTLA4, are expressed on the surface of immune cells, whereas the cognate ligands (PD-L1/PD-L2 and CD86/CD80) are expressed on the tumor cell surface." (PMID 33425739, 2020). "CTLA-4 competes with CD28 for the B7 ligand, inhibiting T cell proliferation and IL-2 secretion, and has been shown to inhibit tumor cell proliferation." (PMID 35582437, 2020). "CD4+Foxp3+Helios+ Treg cells co-expressed the suppressive molecules PD-1, CTLA-4, and CD39, suggesting that the phenotype of these Treg cells in the tumor of CRC patients is highly suppressive." (PMID 32674255, 2020). "This was described for the occurrence of secondary resistance in mice treated with the combination therapy α-CTLA-4 and αPD-1, after cDC1 anti-cancer vaccination and after combined treatment with CPI and an anti-tumor vaccine." (PMID 32290124, 2020).
tumor (continued). "Furthermore, since the novel antibodies do not induce the degradation of CTLA-4, they could provide safe and more efficient anti-tumor responses, differently from those antibodies that trigger degradation of CTLA-4 increasing the toxicity and reducing anti-tumor efficacy, as previously reported." (PMID 32781690, 2020). "Regulatory T-cells, which we have previously shown are depleted from the tumor environment in response to treatment with a FAK inhibitor, represent a major cellular source of CTLA-4." (PMID 31959281, 2020). "Further, the HDAC inhibitor, entinostat, in combination with the checkpoint inhibitors anti–PD-1 and anti–CTLA-4, led to a significant suppression of G-MDSCs in the TME and significantly improved tumor-free survival in HER2/neu transgenic BC mouse model." (PMID 32849585, 2020). "When combined with anti-cytotoxic T-lymphocyte antigen-4 (anti-CTLA-4) treatment, it was shown to reduce of Treg cells and increase of CD8+ T cells infiltration at the tumor site and consequently elevate the survival rate in a mouse model." (PMID 32792853, 2020). "Expansion of an ICOS+ TH1-like CD4+ effector subset was observed in response to CTLA4 blockade; therefore, TH cells, particularly the TH1 cells, are also pivotal players in T-cell mediated anti-tumor immunity and can respond to immunotherapy." (PMID 33329692, 2020). "Tregs combined with CTLA4, LAG3, and TIGIT related to a worse prognosis in RCC exerted immunosuppressive effects, favoring tumor escape from the activity of a variety of antitumor immune effector cells." (PMID 32252440, 2020). "In mice, butyrate restrains anti-CTLA-4-induced up-regulation of CD80/CD86 on dendritic cells and ICOS on T cells, accumulation of tumor-specific T cells and memory T cells." (PMID 32358520, 2020). "Initially, phenotypic analysis was performed to explore CD3, CD4, CD56, PD-1 and CTLA-4 expression on CIK cells and PD-L1/PD-L2 expression on tumor cells." (PMID 32349280, 2020). "Blockade of the interaction between CTLA4 and its ligands, CD80/86 using anti-CTLA4 mAbs can reduce Treg populations leading to increase in effector T cells, thus enhancing anti-tumor immunity." (PMID 32937841, 2020). "We evaluated the lungs of these mice for metastatic nodules and found that numerous tumor nodules were visible on the surface of the lungs of control mice, whereas only mice received both PEG2k-Fmoc-IL36 and CTLA-4 mAbs had significantly fewer lung nodules." (PMID 32351508, 2020). "By targeting T cells regulatory pathways, CTLA-4 monoclonal antibody has been successfully combined with mRNA vaccines in lipid/calcium/phosphate (LCP) NPs, it significantly improved anti-tumor immune response than vaccine alone (Node 4)." (PMID 32408880, 2020). "To further validate this result, we applied the Tumor Immune Dysfunction and Exclusion (TIDE) tool to predict the response of patients to immune checkpoint blockade (CTLA4 and PD1 therapy)." (PMID 32509418, 2020). "Based on the observed increase in [64Cu]NOTA-CD8a tumor-to-heart ratio of the XRT + anti-CTLA-4 group, the [64Cu]NOTA-CD8a tumor-to-heart ratio was plotted for control, TNRs, and TRs." (PMID 32086762, 2020). "In summary, we report therapeutic synergy of NKTR-214 with PD-1 and CTLA-4 CPI therapy and with vaccination in multiple tumor models and mouse strains, accompanied by dramatically increased systemic and intratumoral CD8+ T-cell responses." (PMID 32005826, 2020). "CTLA-4 is also constitutively expressed by the FoxP3+CD4+CD25+ tumor infiltrating regulatory T cells (Tregs), which are important negative regulators of tumor immunity and of autoimmunity." (PMID 32443877, 2020). "The most common immune checkpoint blockage refers to blocking immune inhibitory receptors (CTLA4, PD1 on T cells, or PDL1 on tumor cells and tumor-infiltrating immune cells) using antagonistic antibodies." (PMID 33062192, 2020).
tumor (continued). "PD-1 IHC expression was limited to lymphocytes infiltrating or surrounding tumour nests with higher expression in OSCC compared to actinic cheilitis, while CTLA-4 was expressed in TILs within the TME in contrast to Tregs." (PMID 32708945, 2020). "Consistent with a previous finding that tumor-draining lymphatics are indispensable for checkpoint therapy, we found that CLN-mediated immune activation was essential for anti-PD-1/CTLA-4 efficacy." (PMID 32094452, 2020). "The tumor volume of mice bearing LLC-sgAtrx was significantly shrinked and the median survival of mice was significantly longer after anti-PD1 and anti-CTLA4 treatment." (PMID 33409155, 2020). "Comparable to anti-CTLA-4 mAb, it has been proved that mAbs against OX-40 and GITR are contingent on ADCC-mediated reduction of Tregs to practically inhibit the growth of tumor." (PMID 33519807, 2020). "Immune checkpoint inhibitors, using therapeutic antibodies including anti-CTLA4 and anti-PD1/L1 mAb, to unleash cytotoxic T cells in tumor microenvironment, has achieved great success in clinical practices." (PMID 33613544, 2020). "Recently, PD-L1 has been shown to form a heterodimer with CD80, a shared ligand with CTLA-4 and CD28, in cis on APCs and tumor cells." (PMID 33193345, 2020). "In this second scenario, we have seen that both in naive tumor-free and in tumor-bearing mice, combination of vaccines (either OVA-CIRP or GPC3-CIRP) are more immunogenic in the presence of anti-CTLA-4 and anti-PD-1 antibodies." (PMID 33207844, 2020). "The emerging treatment modality of immunotherapy targets immune checkpoint molecules including PD-1 and its ligand PD-L1, CTLA-4, LAG-3, and TIM-3 to enhance the host immune response against tumours, and to limit the growth and progression of cancer cells." (PMID 32708945, 2020). "The combination of CTLA4 and PD1 blockade increase the anti-tumor efficacy but, concurrently, also the rate of irAEs." (PMID 32290812, 2020). "To validate the efficacy of the anti-CTLA-4 (10 mg/kg, biw, ip) treatment on tumors of different sizes in mice subcutaneously inoculated with CT26 cells xenograft, we measure the tumor size after treatment." (PMID 32805718, 2020). "Flow cytometry revealed that the combination of the anti–CTLA-4 antibody and Tα1 increased the frequency of CD8+ and CD4+ T cells at the tumor site." (PMID 32817121, 2020). "Tumor bearing mice were then treated with ganciclovir (GCV) prodrug therapy, followed by anti-CTLA4 checkpoint inhibitor therapy." (PMID 32034147, 2020). "Anti-cytotoxic T-lymphocyte antigen 4 (CTLA4) and anti-programmed death 1 (PD1)/Programmed death-ligand 1 (PD-L1) monoclonal antibodies have produced long-lasting anti-tumor immune responses that translate into clinical benefits for many cancer types." (PMID 32390761, 2020). "While there is significant variability in the response rates to these drugs based on the tumor type, a recent pooled analysis demonstrated an average objective response rate (ORR) of 14% for anti-CTLA-4 and 33% for anti-PD-1 mAbs." (PMID 33013886, 2020). "Cross-linking of CTLA-4 in these DCs further enhanced the expression of IDO and IL-10, which presumably contributed to immunosuppression and subsequent tumor escape." (PMID 33384695, 2020). "Further, the increase in the [64Cu]NOTA-CD8a tumor-to-heart ratio in tumors of mice treated with XRT and anti-CTLA-4 matched the increased number of CD45+CD8a+ cells detected by flow cytometry in this treatment group." (PMID 32086762, 2020). "The strong positive correlations detected between serum PD-1, PD-L1, CTLA-4 and TNF-α levels also suggest a systemic immunosuppression in cats presenting these tumor subtypes." (PMID 32481540, 2020). "In this study, both CTLA4 immune blockage alone and combination with CD44-targeted PIT increased the T cell infiltration into MOC1 tumor seven days after the treatments, suggesting that primary immune activation was augmented by CTLA4 immune blockade." (PMID 32937841, 2020).